IGF1 (insulin like growth factor 1)
Diseases named in the same sentence as IGF1 in open-access papers (continued):
Sharing a sentence is not in itself a finding about the gene and the disease.
tumor (continued). "The neutrophil-derived serine protease Cathepsin G (CG) promotes the migration of tumor cells via insulin-like growth factor 1 (IGF-1) activation." (PMID 36514901, 2022). "IGF-1 plays a major role in tumor cell proliferation and survival, and its receptor, IGF-1R, plays a significant role in a multi-step process of cancer metastasis." (PMID 36551732, 2022). "Multiple predictive variables [age, gender, preoperative GH and IGF-1 levels, maximal tumor diameter, Hardy’s and Knosp’s grade, MRI." (PMID 36612263, 2022). "In recurrent GBM, the phosphatidylinositol 3-kinase (PI3K) pathway activity, driven by macrophage-secreted insulin-like growth factor-1 (IGF-1) and tumor cell IGF-1 receptor (IGF-1R), was increased." (PMID 35967394, 2022). "The predictive model allowed the formulation of a score for clinical application in which GH and gender were the most powerful predictors for SRL response, adjusted by IGF-1 level, tumor size, and BMI." (PMID 36187107, 2022). "Somatostatin analogs also display indirect antiproliferative effects through the inhibition of circulating growth factors such as vascular endothelial growth factor, insulin-like growth factor 1 and 2, as well as through the inhibition of tumor angiogenesis." (PMID 35838801, 2022). "In our cohort, it showed superior correlations with GH excess and tumor volume than the well-described biomarker IGF-1." (PMID 36042253, 2022). "Afterward, a multivariate analysis was realized, including the previously evaluated variables in addition to others widely evaluated in the literature: age, gender, preoperative GH and IGF-1 levels, maximal tumor diameter, Hardy’s grade, and Knosp’s grade." (PMID 36612263, 2022). "These endocrine features contrast with the autocrine and paracrine characteristics of IGF-1 that originate within the tumor." (PMID 35198099, 2022). "This is the first study to our knowledge that investigated the effect of targeting the IGF-1 pathway on UM tumor growth." (PMID 36551732, 2022). "The Western diet directly promotes tumor cell proliferation via mechanisms involving the insulin/insulin-like growth factor 1 (IGF1)/phosphoinositide 3-kinase (PI3K) signaling pathway." (PMID 35745105, 2022). "Aberrantly increased IGFBP3 impairs IGF1-induced Wnt signaling activation in subsets of basal epithelial cells, directly inhibiting prostatic epithelial oncogenic growth and tumor development." (PMID 36323713, 2022). "Based on these two signal pathways, insulin enhances PDA development through mediating metabolic reprogram, crosstalk with IGF-1, strengthening drug resistance, and stimulating tumor microenvironment (inflammation, fibrosis, and neo-angiogenesis) formation." (PMID 35252207, 2022). "The IGF-1-integrin axis is not only involved in tumor cell invasion but also in the control of tumor cell growth." (PMID 35053528, 2022). "Insulin is regarded as strong growth factor and mitogen which is able to stimulate cell proliferation and inhibit apoptosis and increase bioactivity of IGF-1 to exert tumor-promoting effects." (PMID 35296101, 2022). "IGF1 has previously been shown to regulate the tumor form of pyruvate kinase M2, decrease pyruvate kinase activity, and increase AMP/ATP ratio." (PMID 35840554, 2022). "The correlation with GH excess was 0.368 (p = 0.006; Spearman`s r) for IGF-1 and 0.661 (p < 0.001) for sKl, and with estimated tumor volume 0.276 (p = 0.041) for IGF-1 and 0.527 (p < 0.001) for sKl." (PMID 36042253, 2022). "Before exposing the tumor cells to IGF-1, expression of IGF-1R (DU145) and pIGF-1R (DU145, PC3) was verified by Facs analysis." (PMID 35053528, 2022).
tumor (continued). "The reduced and parsimonious model that best explained SRL response included five predictors: basal GH, basal ULN_IGF-1, gender, maximum tumor diameter, and BMI." (PMID 36187107, 2022). "In a patient-derived xenograft PDAC mouse model, gemcitabine-loaded IGF1-conjugated gold-MSNs reduced tumor growth by around 70%." (PMID 35214121, 2022). "We thus concluded that tumor cells, especially in the G2 stage, are sensitized for IGF1, IGF2 and Insulin stimulation by increased glucose in the TME, as these growth hormones can activate IGF1R." (PMID 35574343, 2022). "At the end of therapy for the hCG-secreting tumor, two patients with pineal lesions had an IGF-1 level higher than 2 SD, and meanwhile only one patient with pineal involvement had an IGFBP-3 level higher than 2 SD." (PMID 36425849, 2022). "High insulin levels also reduce IGF-1-binding proteins and increase free-IGF-1, overactivating the mitogenic effects of the IGF-1 pathway in tumour tissues." (PMID 35681699, 2022). "We have shown in this study that sKl concentrations showed a stronger positive correlation with GH excess and tumor volume than IGF-1 in the pre- and postoperative setting." (PMID 36042253, 2022). "Before and after treatment, we not only evaluated serum GH and IGF-1 levels and tumor size but also analyzed the factors relevant to the effect of the combined therapy." (PMID 35612842, 2022). "A convincing feature was that their relative potency of inhibiting tumor growth coincided with their potency to decrease IGF1 levels and liver weight (summarizing table)." (PMID 35966052, 2022). "Sponging miR-145-5p prevented its inhibitory effect on IGF1 (insulin-like growth factor 1), thereby promoting tumor metastasis." (PMID 33717646, 2021). "Various mechanisms such as altering hormones (androgen, IGF-1, insulin, circulating, and leptin) reduced tumor volume, and reformed antioxidative defense and immune care." (PMID 33927639, 2021). "Because IGF‐1 is well known as a tumor promoter, the current results appear to be conflicting with PAPP‐A tumor suppressor function." (PMID 33788403, 2021). "Insulin and IGF-1 also stimulate β-catenin, a signaling pathway involved in early tumor formation, and the Ras oncogene." (PMID 34359595, 2021). "Meanwhile, another study chemically induced skin carcinogenesis in transgenic mice overexpressing IGF-1 and found that a curcumin diet significantly reduced tumour multiplicity, tumour size, and cell proliferation." (PMID 34867402, 2021). "Of note, dichotomized age, IGF1 xULN at diagnosis, and T2-hypointense signal of the tumor were retained as significant predictors by our multivariable logistic regression model." (PMID 34025586, 2021). "MSCs are able to release a large number of cytokines to exert their tumor regulatory effects, such as interleukin-6 (IL-6), insulin-like growth factor 1 (IGF-1) or vascular epidermal growth factor (VEGF)." (PMID 34095151, 2021). "Growth hormone (GH) has anabolic and mitogenic effects, and insulin-growth factor-1 (IGF-1) is a strong tumor mitogen." (PMID 33713207, 2021). "Chronic exposure to hyperinsulinemia or hyperglycemia induces tumor cell proliferation and metastasis, which increases insulin-like growth factor (IGF)-1 in diabetic patients, stimulates cellular proliferation, and inhibits apoptosis." (PMID 34831299, 2021). "The reduced production of GH and IGF‐1 in animals resists to carcinogenesis, conversely, mice transgenic for human GH have increased rates of tumours." (PMID 33492754, 2021). "Surgical resection of the tumor leads to a decrease in the levels of GH and IGF-1 and thus less insulin resistance in the body." (PMID 33859902, 2021). "Circulating levels of sKlotho are markedly increased in acromegalic patients and return to normal in parallel with GH and IGF-1 levels after tumor removal." (PMID 34143299, 2021).
tumor (continued). "Taken together, we provided molecular evidence of the tumour‐promoting activity of OSF‐derived fibroblast on OSCC cells by showing marked induction of the IGF‐1 production." (PMID 34528373, 2021). "In contrast, myeloid and fibroblastic cells showed differences both between tumor versus WT and G-Smo versus M-Smo tumors, with M-Smo tumors harboring more anti-tumor Cc2+ cells and fewer tumor-promoting Igf1+ cells." (PMID 34021242, 2021). "Multiple signaling pathways such as HGF/c-Met, miR20b, and IGF1/IGFBP2 are involved in the process of ADSCs promoting tumor cell proliferation." (PMID 33407902, 2021). "Both feature selection methods (see Statistical Analysis paragraph) identified dichotomized age, IGF1 xULN at diagnosis, and T2-hypointense signal of the tumor to be retained by our multivariable logistic regression model (p<0.1), while BMI was excluded." (PMID 34025586, 2021). "The largest tumor dimension was significantly correlated to both GH and IGF-1 levels (r = 0.63, p < 0.05)." (PMID 34248479, 2021). "Taken together, these three parameters (dichotomized age, IGF-1 levels, and tumor T2-weighted signal) can provide a satisfactory discriminative ability to predict a >50% IGF-1 reduction after 6-month fg-SRL treatment." (PMID 34025586, 2021). "The overexpression FGF7, FGF9, FGF14, FGF18 and IGF1 genes was found significant in early tumor grades." (PMID 34061869, 2021). "At the diagnosis of tumor, 62/155 (40%) of subjects in group B and 16/42 (38,09%) in group A had active disease (IGF-1 > ULN) (range 7–493% above ULN)." (PMID 33713207, 2021). "Several studies concluded that pre-treatment with SRLs improves surgical remission rate and it was probably related with a reduction of presurgical IGF1 and GH levels and tumor size." (PMID 33289697, 2021). "Considering the anti-apoptosis and mitogenic influences of IGF-1 on normal and cancerous human cells, type 2 DM can promote tumor development." (PMID 34758846, 2021). "Preoperative somatostatin receptor ligands (SRLs) treatment is proven to reduce GH and IGF1 levels and induce tumor shrinkage, improving surgical outcomes in acromegaly." (PMID 33289697, 2021). "CR is shown to decrease IGF-1 (insulin-like growth factor 1), which increases apoptosis and inhibits cell proliferation, thereby delaying tumour progression and expanding longevity." (PMID 33498462, 2021). "Insulin increases the breakdown of IGFBP-3, thus increasing the levels of free IGF-1, promoting tumor formation." (PMID 34359595, 2021). "If residual tumor activity is observed, medical control of GH and insulin-like growth factor 1 (IGF-1) secretion is usually required." (PMID 33671326, 2021). "The first is closely related with the insulin-like growth factor 1 (IGF-1) receptor pathway.Insulin can directly or indirectly affect the occurrence of tumor through IGF-1, a powerful mitogen." (PMID 33468224, 2021). "The somatostatin analogue therapy was maintained for 2 years after surgery and cabergoline was added on, but GH and IGF-1 levels remained in high range with continued tumor growth." (PMID 34461869, 2021). "Activation of IGF-1R following binding of IGF-1 has been shown to be involved in tumor cell growth and survival." (PMID 33557137, 2021). "The tumor-suppressive effect mediated by ITGA11 knockdown was attenuated after activating the PI3K/AKT pathway with insulin-like growth factor 1 (IGF-1)." (PMID 34802381, 2021). "For example, CSF-1 is a vital factor inducing M0-to-M2 polarization, TGF-β induces differentiation and activation of Tregs, and IGF-1 is positively correlated to tumor sizes in NPC patients." (PMID 34568077, 2021).
tumor (continued). "Olig2-expressing tumor stem cells, Ccr2+ macrophages, and Igf1+ microglial have all been shown to affect tumor progression and prognosis." (PMID 34021242, 2021). "High concentrations of insulin-like growth factor-1 (IGF-1) and insulin promote carcinogenesis and early tumor growth through anti-apoptotic signaling and PI3K-Akt-mTORC1-mediated metabolic reprogramming." (PMID 33430318, 2021). "PHD normally promotes hypoxia-inducible-factor 1-alpha (HIF1) breakdown through hydroxylation and reduction in this function leads to a pseudo-hypoxic state with associated upregulation of a range of genes that can promote neoplasia (e.g. IGF-1 and VEGF)." (PMID 33854214, 2021). "The results showed that the levels of APN, IGF-1, and IGFBP-3 are not significantly different between PTC, FTC, and MTC but that the ratio of IGF-1/APN and IGF-1/(APN×IGFBP-3) ratio is independently related to tumor size." (PMID 33815885, 2021). "Insulin inhibits the production of IGF-1-binding proteins from the liver, which leads to an increased concentration of biologically active free IGF-1, which is involved in tumor promotion." (PMID 34638244, 2021). "At the same time, osteoclast bone resorption can lead to the release of pro-tumor factors as IGF-1 (Insulin Growth Factor 1) and TGF-β from the bone matrix that stimulate tumor cells." (PMID 34830463, 2021). "IGF1 activates the cell proliferation pathway and inhibits cell apoptosis, which is involved in tumor growth and is required for B cell-independent T cell activation, the hallmark of SLE." (PMID 34646335, 2021). "The expression of RCC2 in ER-positive breast induces the expression of IGF-1 and leads to the malignant behavior of tumor cells, including proliferation, invasion, etc.." (PMID 33750478, 2021). "Both whole transcripts and the mature IGF-1 protein are detected in a wide variety of normal and tumor cells (reviewed in:)." (PMID 34208601, 2021). "IGF-1, a physiological regulator of growth in the human body, is involved in tumour metabolism by regulating cell proliferation, clonal growth, and migration." (PMID 34177367, 2021). "With consistent up/down-regulation in multiple tissues, the tumor suppressor miR-425 is able to repress the PI3K-Akt pathway by targeting IGF-1." (PMID 32849809, 2020). "Studies have shown that AF has antineoplastic effects, such as inhibition of tumor growth and tumor cell proliferation, and decreased insulin-like growth factor-1 (IGF-1) levels." (PMID 32028692, 2020). "Accumulating evidence suggests a major role of αKlotho as a tumor suppressor, at least in part by inhibiting IGF-1 and Wnt/β-catenin signaling." (PMID 33520985, 2020). "In a phase I, dose escalation study, pasireotide concentrations showed a direct relationship with tumor shrinkage and an inverse relationship with IGF-1 levels." (PMID 32121432, 2020). "The human IGF1 gene is composed of six exons, four of which are alternatively spliced (AS) and is transcribed in a wide variety of normal and tumor cells." (PMID 32977489, 2020). "Our results suggest that increased RCC2 expression stimulates tumor growth by upregulating IGF1, TWIST1, and IL-6 expression." (PMID 32565805, 2020). "In tumor cells, the IGF-1 signaling drives neoplastic behaviors, as well as protects tumors from cytotoxic treatment likely through promoting the activity of efflux pumps while upregulating double-strand break repair." (PMID 32512898, 2020). "Unexpectedly, we found that, in addition to efficiently activate IGF1R, IGF1 also induced the phosphorylation of PDGFRα in mouse tumor OPCs." (PMID 33173731, 2020). "Consistent with their expression in TAMs, MMP-9 and IGF-1 expression was also significantly decreased in the infected tumor tissue; however, the expression of VEGF was only slightly decreased in the infected tumors compared with the uninfected tumors." (PMID 32972437, 2020).
tumor (continued). "Insulin, as it was described in the previous section, promotes the synthesis and activity of IGF-1 as well as mitosis and cell proliferation and thus, it exerts tumour growth-stimulating effects." (PMID 33008076, 2020). "It has been reported that adipocytes and MSCs from human lipoaspirate of obese donors, compared to adipocytes/MSCs from lean subjects, enhance BC cell growth at higher extent and promote tumor metastasis at least in part by IGF1 and leptin pathways." (PMID 32850459, 2020). "In preclinical experiments, fasting reduces tumor progression and sensitizes different tumor types to chemotherapy, while protecting normal cells through a mechanism that can involve the reduction of blood IGF-1 and glucose levels." (PMID 32393788, 2020). "Chemotherapy suppresses IGFBP17 in TECs, which leads to the upregulation of IGF1 in tumor cells and activation of the stem cell-like properties of tumor cells." (PMID 32283668, 2020). "It has proven to be highly effective in the normalization of IGF-1 levels in more than 90% of patients, to improve the quality of life, and to decrease tumor size in 20% of patients." (PMID 32121432, 2020). "Locally produced GH and IGF-1 in the tumor microenvironment imparts autocrine and paracrine effects to drive tumor growth in multiple ways." (PMID 33291663, 2020). "Contrary to a significantly low level of Gh and Igf-1 transcript levels in vitro, we detected GH and IGF-1 proteins in the tumor lysates in vivo." (PMID 33291663, 2020). "This has a direct effect by increased binding of insulin to the tumour cell’s insulin-receptor and an indirect effect by increasing the concentration of free insulin-like-growth-factor-1 (IGF-1), resulting in increased tumour growth." (PMID 32210471, 2020). "In OSs, osteoclast activity leads to a vicious cycle between OS cell proliferation and bone degradation, leading to the release of pro-tumor factors such as insulin-like growth factor 1 (IGF1) or transforming growth factor-β (TGF-β) from the bone matrix." (PMID 32326444, 2020). "Other evidence has demonstrated that IGF1 stimulation remarkably enhanced the migratory capacity of tumor-derived PSC." (PMID 32414222, 2020). "Western blot analysis demonstrated that circPLK1 silence decreased the protein level of IGF1 in tumor tissues (P < 0.001)." (PMID 33298061, 2020). "In conclusion, we report that MMP11 inhibits cell death and promotes tumor growth by activating the IGF1/AKT/FoxO1 pathway in the MMTV-PyMT mouse model of mammary gland tumor." (PMID 32825455, 2020). "For a long period, it was believed that tumor cells synthesize IGF-1 to arbitrate autocrine and paracrine stimulation of IGF1R signaling cascade in PDAC cells." (PMID 32414222, 2020). "Mouse astrocytes expressed very low amounts of Igf1 and Igf2 mRNA, while in HAs both Igf1 and Igf2 mRNA levels were higher than in tumor cells, but still lower than in pericytes." (PMID 32534480, 2020). "Altogether, these data showed that circPLK1 downregulation inhibited tumor growth by upregulating miR-4500 and downregulating IGF1." (PMID 33298061, 2020). "On the other hand, IGF-1 promotes tumor cell invasion and inhibits tumor suppressor phosphatase and tensin homolog (PTEN)." (PMID 32393273, 2020). "IGF-1 signaling axis is a key mechanism that promotes PDAC tumor-stromal crosstalk and drug resistance." (PMID 32660466, 2020). "In summary, our study demonstrated that IGF1 was overexpressed in PTC tissue and was significantly associated with tumor size, TNM staging, and Lymph node metastasis." (PMID 32851683, 2020). "We next analyzed gene expression of TLR4 and IGF-1, both known to be expressed by tumor-infiltrating mononuclear cells and to a certain extent by tumor cells." (PMID 32425932, 2020). "Together, these results show that HZ plays an important role in the reduction of IGF-1 expression in TAMs of Plasmodium-infected tumor-bearing mice." (PMID 32972437, 2020).